CXCL13 (C-X-C motif chemokine ligand 13)
Diseases named in the same sentence as CXCL13 in open-access papers (continued):
Sharing a sentence is not in itself a finding about the gene and the disease.
autoimmune disease (continued). "Ectopic germinal center-like lymphoid structures have been recognized within the affected tissues in numerous autoimmune diseases, including myasthenia gravis and rheumatoid arthritis, long before the cloning of CXCL13 and CXCR5." (PMID 31354634, 2019). "Whereas, the CXCL13:CXCR5 axis has been best characterized in these autoimmune disorders through the aberrant activity and differentiation of B-cells, numerous other autoimmune conditions appear to be driven by T follicular helper cells TFH cells." (PMID 31354634, 2019). "We also detected elevated levels of chemokine CXCL13 and its receptor CXCR5 which involve the maintenance of pathogenic B cells in autoimmune diseases like MS." (PMID 29503661, 2018). "CXCL13 plays an important role in the formation of the GC in ectopic lymphoid follicles of several organs affected by inflammatory or autoimmune disease, or by infection." (PMID 30345018, 2018). "Abnormal overexpression of CXCL13 is observed in many inflamed tissues and in particular in autoimmune diseases." (PMID 26771137, 2016). "B-cells are known to play an important role in various autoimmune diseases including multiple sclerosis (MS) where areas of demyelinating lesions attract B-cells by overexpressing CXCL13, the CXCR5 ligand." (PMID 27909439, 2016). "We developed a novel therapeutic antibody targeting CXCL13-mediated signaling pathway for the treatment of autoimmune disorders." (PMID 25879435, 2015). "High expression of CXCL13 has been found previously in many autoimmune diseases, such as myasthenia gravis, multiple sclerosis, and in a model mouse of SLE, and is considered to be associated with autoantibody production." (PMID 20856892, 2010). "CXCL13 in serum is one of the candidates with reports of correlation with prognosis and activity in autoimmune diseases, but there is still no consensus regarding its association with TLSs." (PMID 41029827, 2025). "Also, a novel therapeutic antibody targeting CXCL13-mediated signaling pathway has been postulated for the treatment of autoimmune disorders." (PMID 38691538, 2024). "Moreover, CXCL13 is also related to many autoimmune diseases, such as rheumatoid arthritis (RA), multiple sclerosis (MS), systematic lupus erythematosis (SLE), primary Sjögren’s syndrome (pSS), myasthenia gravis (MG), and inflammatory bowel diseases (IBD)." (PMID 35309354, 2022). "CXCL13 is also involved in the initiation and organization of ectopic lymphoid-like structures (ELSs), the organized lymphocyte aggregates developed at sites of inflammation in target tissues of autoimmune diseases." (PMID 35309354, 2022). "Expression levels and effects of CXCL13/CXCR5 axis in autoimmune diseases." (PMID 35309354, 2022). "Recent studies have found that CXCL13 and its receptor CXCR5 are implicated in the pathogenesis of several autoimmune diseases, such as rheumatoid arthritis, multiple sclerosis, systemic lupus erythematosus, primary Sjögren’s syndrome, myasthenia gravis, and inflammatory bowel disease." (PMID 35309354, 2022). "Indeed, numerous preclinical studies support the concept of suppressing the CXCL13/CXCR5 axis as a novel therapeutic approach for autoimmune diseases treatment." (PMID 35309354, 2022). "CXCL13 plays a crucial part in infectious, inflammatory and immune responses and is closely related to the pathogenesis of numerous lymphoproliferative disorders, inflammatory and autoimmune diseases." (PMID 35141160, 2022). "Furthermore, we discuss the potential role of CXCL13 as a disease biomarker and therapeutic target in autoimmune diseases." (PMID 35309354, 2022). "Due to its essential role in immune regulation and inflammatory response, CXCL13/CXCR5 axis may serve as a potential therapeutic target for autoimmune diseases." (PMID 35309354, 2022). "Besides, CXCL13/CXCR5 axis plays similar roles in other autoimmune diseases, such as MS, SLE, MG, and so on." (PMID 35309354, 2022).
autoimmune disease (continued). "However, there has been only limited research on the function of CXCL13/CXCR5 axis in these autoimmune diseases, and more studies are required to provide further insights." (PMID 35309354, 2022). "Therapeutic effects on targeting CXCL13/CXCR5 axis in autoimmune diseases." (PMID 35309354, 2022). "Interestingly, therapeutic agents targeting CXCL13/CXCR5 are currently being explored in the context of autoimmune disease and non-Hodgkin lymphoma." (PMID 34615710, 2021). "Indeed, CXCL13 is involved in the pathogenesis of several autoimmune diseases and inflammatory conditions by regulating lymphocyte infiltration within the microenvironment." (PMID 34566966, 2021). "In support of this, serum CXCL13 has been identified as a biomarker of GC activity and production of antibodies after vaccination and of systemic immune activation and disease activity in both infection and autoimmune diseases." (PMID 34484201, 2021). "Treatment with anti-CXCL13 antibodies mitigated disease in murine models of autoimmune disease." (PMID 31921124, 2019). "While its role(s) in the pathogenesis of neoplastic, infectious and autoimmune disorders of the CNS remain incompletely understood, growing evidence suggests that CXCL13 could become a relevant therapeutic target in at least some of these conditions." (PMID 28603659, 2016). "We, therefore, hypothesized that antibody-mediated disruption of the CXCL13 signaling pathway would interfere with the formation of ectopic lymphoid follicles in the target organs and inhibit autoimmune disease progression." (PMID 25879435, 2015). "In addition, the CXCL13/CXCR5 axis may also have disease-specific pathogenetic mechanisms in certain autoimmune diseases, which will be discussed further below." (PMID 35309354, 2022). "Interestingly, CXCL13 and CSF2 have been associated with autoimmune diseases." (PMID 35784351, 2022). "In addition, in the clinical setting, glucocorticoid and DMARDs can alleviate the symptoms of autoimmune diseases and reduce the expression of CXCL13, suggesting that CXCL13 may reflect treatment response." (PMID 35309354, 2022). "In addition, recent studies have revealed that CXCL13/CXCR5 may also have a disease-specific pathological mechanism in some autoimmune diseases." (PMID 35309354, 2022). "However, due to the heterogeneity of autoimmune diseases, the clinical significance of CXCL13 may be different for patients with different disease subtypes, different stages of progression, and different genetic backgrounds." (PMID 35309354, 2022). "In addition to autoimmune diseases, CXCL13 is also regarded as a prognostic biomarker for IPF." (PMID 35309354, 2022). "However, the specific mechanism through which CXCL13 plays a role in autoimmune diseases is still largely unknown." (PMID 35309354, 2022). "Hence, CXCL13 may affect the pathogenesis of autoimmune diseases through regulating ELSs development." (PMID 35309354, 2022). "We also detect and characterize tertiary lymphoid structures marked by CXCL13/CXCR5 and CCL19-mediated signaling from Tph cells and immunoregulatory DCs, analogous to those observed in other autoimmune diseases." (PMID 41269758, 2025). "Moreover, CXCL13 combined with other biomarkers may be helpful for the diagnosis of some autoimmune diseases, but the optimal cut-off value should be determined according to specificity and sensitivity, and their diagnostic efficacy should be carefully evaluated." (PMID 35309354, 2022). "C-X-C Motif Chemokine Ligand 13 (CXCL13) plays a crucial part in the pathogenesis of numerous lymphoproliferative disorders, inflammatory responses, and autoimmune diseases." (PMID 35141160, 2022). "In autoimmune diseases such as rheumatoid arthritis (RA), we showed that TGF-β and other proinflammatory cytokines enhanced CXCL13 production by CD4+ T cells and that CXCL13-producing CD4+ T cells had an important role in the formation of TLS." (PMID 35552285, 2022).
autoimmune disease (continued). "In animal models of autoimmune diseases, knockout or neutralization of CXCL13/CXCR5 significantly improve clinical symptoms, suggesting that CXCL13/CXCR5 can be used as a therapeutic target for autoimmune diseases." (PMID 35309354, 2022). "Additionally, plasma CXCL13 has been associated with immune activity in various infectious and autoimmune diseases, suggesting that it may not be a specific marker of germinal center activity." (PMID 31333650, 2019). "Overall, dysregulation of the CXCL13:CXCR5 axis affecting both B- and TFH cell function is major player in autoimmune disorders, and potentially serves as a biomarker for disease progression and therapeutic response." (PMID 31354634, 2019). "In fact, in a number of the autoimmune disorders (e.g., MS, SLE, Sjogren’s syndrome and RA), CXCL13 is considered a biomarker indicative of disease severity." (PMID 25879435, 2015). "CD274 (PD-L1), CXCL13, BIRC5, and SMPD3 play the following roles in the IL-17a and IL-23 pathways: CD274 (PD-L1): The IL-17a and IL-23 pathways are closely related to the pathogenesis of autoimmune diseases like psoriasis." (PMID 40557155, 2025). "Furthermore, serum levels of CCL8, CXCL13, and IL-1RA were also higher in patients with SLE compared with patients with other autoimmune diseases and were moderately correlated with global SLE disease activity." (PMID 38098483, 2023). "Interestingly, recent reports have focused on the role of CXCL13 and its receptor “CXCR5” as a B-cell chemoattractant, especially in autoimmune diseases." (PMID 35457267, 2022). "To summarize, these results suggest that the CXCL13/CXCR5 axis is a promising target for autoimmune diseases, which may open avenues for novel strategies for autoimmune diseases treatment." (PMID 35309354, 2022). "With regard to autoimmunity, CXCL13 elevations in the blood occur in SLE, RA, SS, MS, and MG, and are proposed biomarkers for disease activity, treatment response, and treatment targets for autoimmune disorders." (PMID 36078057, 2022). "Moreover, the interaction of CXCL13 with its specific receptor CXCR5 enhances B-cell maturation and the synthesis of antibodies in autoimmune diseases." (PMID 34518512, 2021). "CXCL13 and CXCR5 are in fact involved in normal lymphocyte trafficking and homing in secondary lymphoid organs and are highly expressed in various autoimmune diseases characterized by the occurrence of ectopic lymphoid follicles, which are also a prominent feature of AIPC." (PMID 18596913, 2008). "It has been found that, during EAE, CXCL13 and BAFF mRNAs are induced intracerebrally and CXCL13-producing cells can be detected in the meninges of these mice suggesting that these tissue sites may be responsible for inducing autoimmune disease." (PMID 34975310, 2022). "This brings us to CXCL13 as a soluble part of the CXCL13/CXCR5 immune axis, which is, as is the case for cTfh cells, physiologically detectable in blood and increased upon immune activation in the same contexts of infection, vaccination, and autoimmune disorders." (PMID 36078057, 2022). "Furthermore, CXCL13/CXCR5-associated immune activities occur in non-lymphoid tissues, where they contribute to organizing and shaping in situ adaptive immune responses via the formation of ELS at chronic inflammatory sites during persistent infections, autoimmune diseases, and cancer." (PMID 36078057, 2022). "IPF is not considered a classical autoimmune disease; however, it has been reported that IPF patients express some features of classical autoimmunity such as elevated CXCL13 expression." (PMID 31098385, 2019).
multiple sclerosis (64 papers, 2010 to 2026). A progressive autoimmune disorder affecting the central nervous system resulting in demyelination. "The inflammatory chemokine CXCL13 is associated with the chronic inflammatory conditions severe rheumatoid arthritis and multiple sclerosis." (PMID 37082114, 2022). "In addition, the potential diagnostic value of CXCL13 as a biomarker reflecting disease activity was recently evaluated in multiple sclerosis." (PMID 38674602, 2024). "However, CXCL13 is not only discussed as a potential diagnostic and treatment response biomarker in neuroborreliosis but also in primary CNS lymphoma and multiple sclerosis." (PMID 38203597, 2023). "Elevated levels of Cxcl13 have been studied in the context of neuroimmunological diseases, such as multiple sclerosis and ALS." (PMID 41282248, 2025). "CXCL13 is a chemokine which is upregulated within the CNS in multiple sclerosis, Lyme neuroborreliosis, and other inflammatory diseases and is increasingly clinically useful as a biomarker." (PMID 39766248, 2024). "They found the combination of chitinase-3-like-1, CXCL10, CXCL12, CXCL13 increased the AUC for predicting conversion to clinically definite multiple sclerosis after first attack above any single biomarker in isolation." (PMID 38368354, 2024). "Since higher CXCL13 expression also worsens rheumatoid arthritis or multiple sclerosis, its function is considered to promote inflammatory pathways." (PMID 37304286, 2023). "All patients with elevated CSF CXCL13 levels showed a concurrent inflammatory disease (one patient each with multiple sclerosis, sarcoidosis and rheumatic disease) and elevated CXCL13 levels were significantly associated with intrathecal IgG synthesis." (PMID 37000850, 2023). "CXCL13 in cerebrospinal fluid is a prognostic marker in Clinically Isolated Syndrome regarding conversion to multiple sclerosis." (PMID 37304286, 2023). "A PubMed search of “CXCL13”,”biomarker”,and “multiple sclerosis” reveals that prior to 2008 there were only 3 articles identified while after 2008 there were 72 such papers." (PMID 36140203, 2022). "CXCL13 expression has also been observed in models of multiple sclerosis, particularly in cerebrospinal fluid and meningeal tertiary lymphoid organs." (PMID 35787714, 2022). "CXCL13, a vital immune inflammatory response factor, was reported to be involved in the occurrences of CNS diseases such as multiple sclerosis (MS), primary CNS lymphoma, epilepsy, cerebrospinal meningitis, and meningitis." (PMID 36389787, 2022). "Related to autoimmunity, several complementary studies demonstrated that CXCL13 is an important mediator of human autoimmune disorders, such as rheumatoid arthritis, systemic lupus erythematosus, multiple sclerosis and myasthenia gravis." (PMID 34869409, 2021). "Elevated levels of CXCL13 have been reported in the cerebrospinal fluid of patients with multiple sclerosis or neuromyelitis optica, and it has even been proposed as a biomarker for these neurodegenerative conditions." (PMID 33161894, 2020). "CXCL13 has been proposed as a biomarker of neuroinflammatory disease due to its high level in the CNS under a variety of conditions, including multiple sclerosis and neuromyelitis optica as well as CNS lymphoma." (PMID 33161894, 2020). "The chemokine CXCL13 specifically recruits B cells for diapedesis into brain parenchyma, and is upregulated by inflammatory mechanisms in multiple sclerosis." (PMID 24485041, 2014). "CXCL13 is upregulated in the CNS by infiltrating immune cells at sites of multiple sclerosis lesions and in preclinical studies during CNS infection." (PMID 24485041, 2014). "CXCL13 has recently been suggested as a prognostic marker for multiple sclerosis and clinically isolated syndrome (CIS)." (PMID 22591862, 2012).
multiple sclerosis (continued). "Our findings are consistent with previous studies, which suggested CXCL13 to be an essential chemokine in controlling the recruitment of B cells to the CNS in specific inflammatory diseases like multiple sclerosis and Lyme neuroborreliosis." (PMID 22591862, 2012). "What is the relevance of the CXCL13 index in multiple sclerosis?" (PMID 40165834, 2025). "Previous studies have shown that both serum and cerebrospinal fluid levels of CXCL13 are elevated in NMOSD patients compared with those with multiple sclerosis and healthy controls, potentially promoting neuroinflammation by recruiting antibody-secreting B cells." (PMID 41567208, 2025). "In addition, CXCL13 levels in CSF were significantly elevated in multiple sclerosis with clinical (p = 0.001) and radiographic disease activity (p < 0.001)." (PMID 38203597, 2023). "High CXCL13 levels in the cerebrospinal fluid were demonstrated to correlate with increased B-cell recruitment in the CNS in a number of human disorders such as lymphoma, Lyme disease and multiple sclerosis (MS)." (PMID 33803478, 2021). "The mean concentrations of CSF CXCL13 in glioblastomas, other gliomas, germ cell tumors, metastatic tumors, other tumors, multiple sclerosis, iNPH, and other diseases were 21 ± 214, 24 ± 45, 38 ± 77, 176 ± 390, 4 ± 3, 36 ± 72, 14 ± 31, and 233 ± 498 pg/mL, respectively." (PMID 32314548, 2020). "CXCL13, a B-cell chemoattractant, drives the organization of the meningeal tertiary lymphoid organs, as described in RA synovitis and correlates with intrathecal IgG production in antibody-mediated CNS disorder (neuromyelitis optica) and multiple sclerosis." (PMID 32471260, 2020). "Similarly anti-CXCL13 antibody demonstrated efficacy in mouse models of autoimmunity including multiple sclerosis by reducing B cell infiltration and subsequent interactions with T cells." (PMID 27575749, 2016). "Furthermore, elevated levels of CXCL13 have been reported in the cerebrospinal fluid (CSF), active plaques, and meningeal ectopic follicles of patients with multiple sclerosis (MS), and thus, is considered to be a biomarker for MS and other neuroinflammatory diseases." (PMID 36157272, 2022). "Moreover, CXCL13 could be a biomarker of inflammation in a diversity of diseases, including multiple sclerosis, neuromyelitis optica and rheumatoid synovium." (PMID 36613500, 2022). "CXCL13 levels were upregulated in synovial tissue and plasma from patients with rheumatoid arthritis, in serum and plasma from patients with systemic lupus erythematosus, in CSF from patients with multiple sclerosis and in serum from patients with myasthenia gravis." (PMID 34869409, 2021). "CXCL13 binds the CXCR5 receptor and regulates homing of B cells and, recently it has been suggested as a prognostic marker for multiple sclerosis (MS), another chronic inflammatory autoimmune disease." (PMID 38691538, 2024). "In particular, people with multiple sclerosis on natalizumab had lower CD6, CDCP1, CXCL13, CXCL9, NfL, TNFRSF10a, TNFSF13B and VCAN (P < 0.036)." (PMID 37361716, 2023). "CXCL13 expression has been correlated with disease exacerbation and unfavorable prognosis in multiple sclerosis, Sjögren's, myasthenia gravis, and SLE, and CXCL13 has been proposed as a biomarker for diagnosis and progression in these conditions." (PMID 31354634, 2019). "CXCL13 has been shown to be useful to monitor clinical progression and response to treatment in particularly in Lyme disease, anti-NMDAR encephalitis, multiple sclerosis and B cell lymphoproliferative disorders." (PMID 27575749, 2016). "Expression of CXCL13, which binds CXCR4 receptor and regulates B cell migration, has been reported to be enhanced in inflammatory CNS diseases, such as multiple sclerosis and encephalitis." (PMID 27894304, 2016). "CSF CXCL13 is highly specific in neuroinflammatory conditions, such as multiple sclerosis, and is little expressed in non-inflammatory states of the CNS." (PMID 41164191, 2025).